GDF15 (growth differentiation factor 15)
Diseases named in the same sentence as GDF15 in open-access papers (continued):
Sharing a sentence is not in itself a finding about the gene and the disease.
multiple myeloma (continued). "In summary, our results indicated that recombinant GDF15 activated SMAD2 in myeloma cells, possibly through the same receptors as TGF-β." (PMID 29161287, 2017). "In multiple myeloma, Growth Differentiation Factor 15 (GDF15) is secreted by bone marrow stromal cells in response to differentiated tumor cells and enhances tumor-initiating potential and self-renewal." (PMID 28692661, 2017). "Elevated GDF-15 showed a significant and independent role in prognosis for overall mortality over other biomarkers such as NT-proBNP and TnT, where elevated biomarkers indicate a worse prognosis in AL-amyloidosis." (PMID 39781722, 2025). "In addition, GDF15 secreted by bone marrow stromal cells has been reported to contribute to tumor initiation and self-renewal of multiple myeloma cells." (PMID 38201456, 2023). "GDF-15 is another potential mediator that plays a role within the myeloma microenvironment." (PMID 35334593, 2022). "GDF-15 may therefore be a molecule reflecting myeloma burden as a consequence of the progressive disease, and therefore, its assessment throughout the management does not hold more favorable prognostic significance to the staging system itself." (PMID 33144847, 2020). "Prior studies in homogenous samples (i.e., incident myeloma cases) have already demonstrated that GDF-15 is a candidate marker in myeloma, yet the majority of patients that stand to benefit from biomarker assays throughout the management are not treatment-naive." (PMID 33144847, 2020). "GDF-15 may be a valuable molecule to investigate in biomarker-based models accounting for the complexity of myeloma biology." (PMID 33144847, 2020). "This may indicate that in cases of partial vs. complete remission, the tumor microenvironment exerts a protective effect on myeloma cells, which is reflected in circulating GDF-15 concentrations similar to stable or progressive disease." (PMID 33144847, 2020). "Due to the correlations between GDF-15 and other markers of myeloma burden, which are also indicators of renal injury (e.g., β2 microglobulin), it is also conceivable that the pronounced concentrations of GDF-15 apparent at more advanced stages of disease relate to impaired glomerular filtration." (PMID 33144847, 2020). "Whether GDF-15 is a key player in the processes shaping kidney injury or it is intertwined with myeloma progression and resulting end-organ sequelae remains to be established." (PMID 33144847, 2020). "There is a recent report suggesting that GDF15 may function in CSCs from multiple myeloma, a relatively rare subtype of hematological malignancy." (PMID 28206960, 2017). "For the stemness phenotype, GDF15 has been previously reported to participate in the cellular differentiation of osteoblasts and to enhance tumor initiation and malignancy in multiple myeloma cells." (PMID 27903972, 2017). "The initial aim of this study was to show by which receptor(s) GDF15 could signal by use of the myeloma cell lines and other relevant cell types." (PMID 29161287, 2017). "In addition, serum levels of GDF15 were reported to be elevated in patients with multiple myeloma (MM), and bone marrow (BM) mesenchymal stromal cells (MSCs) from these patients were shown to express high levels of GDF15 19–22." (PMID 26276681, 2015). "In multiple myeloma where GDF-15 is produced by bone marrow stromal cells rather than by the tumor, increased GDF-15 serum levels were associated with a tumor-promoting microenvironment, as demonstrated by enhanced clonogenic growth of multiple myeloma cells and reduced progression-free survival." (PMID 32508832, 2020). "The underlying mechanism of GDF-15 in both MM- and AL-related renal pathology is unclear, though in AL-amyloidosis, it has been suggested that GDF-15 plays a direct role in pathophysiology, and its production may be induced following a response to free light chain toxicity." (PMID 33144847, 2020).
multiple myeloma (continued). "SERPINE1 (together with ANGPTL4, GDF15, CXCL12, SOX9, HOXB6, and ANK3) was even described as a TA-MSC factor, namely, in mesenchymal stromal cells of the bone marrow that supported myeloma cell growth." (PMID 39011489, 2024). "Levels of sST2, GDF15, and OPN were quantified at diagnosis in a total of 73 AL amyloidosis patients at Samsung Medical Center from 2010 to 2016." (PMID 31434944, 2019). "Addition of GDF15 dose-dependently and time-dependently activated SMAD2 in THP-1 cells in a manner like in the myeloma cell lines." (PMID 29161287, 2017). "From our results, sST2 and GDF-15 showed satisfactory discriminative values for overall survival in AL amyloidosis patients, while OPN did not." (PMID 31434944, 2019). "Additionally, accumulating evidence indicates that ATM drives the BM-mediated resistance to chemotherapy in other hematological malignancies, such as multiple myeloma and acute lymphoblastic leukemia via upregulation of cytokines such as IL-6 or CCL3, CCL4, and GDF15." (PMID 36259537, 2022). "However, prognostic value of novel biomarkers, such as soluble suppression of tumorigenicity 2 (sST2), growth differentiation factor 15 (GDF15), or osteopontin (OPN) is unknown in AL amyloidosis." (PMID 31434944, 2019). "We found that recombinant human GDF15 activated SMAD2, but not SMAD1/5 in the multiple myeloma cell line IH-1." (PMID 29161287, 2017).
chronic obstructive pulmonary disease (27 papers, 2017 to 2026). A chronic and progressive lung disorder characterized by the loss of elasticity of the bronchial tree and the air sacs, destruction of the air sacs wall, thickening of the bronchial wall, and mucous accumulation in the bronchial tree. "In chronic obstructive pulmonary disease (COPD), which is associated with cigarette smoking, a positive association has been found between elevated levels of GDF-15 and exacerbation frequency as well as impairment of pulmonary function." (PMID 35251002, 2022). "In chronic obstructive pulmonary disease (COPD), high levels of plasma GDF15 have been associated with increased exacerbations." (PMID 35993367, 2022). "High levels of GDF15 have been observed in certain pulmonary diseases, including chronic obstructive pulmonary disease (COPD) and PAH." (PMID 34445593, 2021). "In chronic obstructive pulmonary disease, GDF-15 contributes independently to subclinical coronary atherosclerosis." (PMID 33201838, 2020). "GDF15 has been reported in the airway epithelium of smokers with chronic obstructive pulmonary disease and in human airway epithelial cells exposed to cigarette smoke." (PMID 31847237, 2019). "In patients with chronic obstructive pulmonary diseases, elevated GDF-15 levels may be explained by intrathoracic mechanics and hypoxia." (PMID 41597417, 2026). "Moreover, GDF15 muscle and serum levels inversely correlate with muscle cross-sectional area in chronic obstructive pulmonary disease (COPD) patients and with muscle force in lower limb mobility impairments." (PMID 33374852, 2020). "In this context, elevated GDF-15 levels have been recently found during early chronic obstructive pulmonary disease (COPD)." (PMID 34920697, 2021). "Growth differentiation factor-15 (GDF-15), a cytokine associated with cardiovascular mortality, increases during chronic obstructive pulmonary disease (COPD) exacerbations, but any role in stable COPD is unknown." (PMID 28245821, 2017). "Plasma GDF15 concentrations in patients with PVOD, idiopathic PAH (IPAH), heritable PAH (HPAH), group 2–4 PH (Other PH), and chronic obstructive pulmonary disease without PH (COPD) as well as individuals acting as healthy controls were quantified." (PMID 41264364, 2026).
dementia (27 papers, 2015 to 2026). Loss of intellectual abilities interfering with an individual's social and occupational functions. "In UKB, proteins associated with earlier menopause, including GDF15, exhibited concordant associations with incident dementia risk and brain atrophy, cerebral small vessel disease burden, and white matter microstructural integrity." (PMID 42147192, 2026). "Leveraging two external cohorts, we subsequently found DNAm CRP was associated with 18‐ and 25‐year dementia risk, whereas the results were mixed for DNAm GDF15." (PMID 41274863, 2025). "Extensive research, including large-scale cohorts such as the Whitehall II study, the Atherosclerosis Risk in Communities (ARIC) study, and the UK Biobank, has consistently associated elevated GDF15 levels with a heightened risk of dementia [1278–1282]." (PMID 40407975, 2025). "The present study used an epigenetic and proteomic approach to characterize two measures of chronic inflammation—CRP and GDF15 DNAm—and examine their associations with structural brain and cognitive trajectories, as well as dementia risk." (PMID 41274863, 2025). "DNAm and plasma GDF15 were similarly associated with several total lobar, total lobar white matter, and AD‐relevant region trajectories and dementia risk, but DNAm measures outperformed plasma measures in relation to cognitive trajectories." (PMID 41274863, 2025). "A one standard deviation increase in DNAm GDF15 and plasma GDF15 was associated with a 16% [HR: 1.16; 95% CI: 1.07–1.27, p = 0.0004] and 27% [HR: 1.27; 95% CI: 1.16–1.39, p = 2.5E07] increase in dementia risk, respectively, after age and sex adjustment." (PMID 41274863, 2025). "Upregulated blood GDF15 was further revealed to be associated with risk of dementias, neurodegenerative diseases affecting cognition, including AD." (PMID 39737171, 2024). "Another study found a correlation between elevated GDF15 and AD Pattern Similarity (AD-PS) score, an index of neuroanatomical dementia risk that compares grey matter spatial patterns." (PMID 39737171, 2024). "Sensitivity analyses showed higher GDF15 was significantly associated with higher dementia risk and worse cognitive function." (PMID 37178386, 2023). "Higher cerebrospinal GDF15 levels were also associated with increased risk of incident dementia and lower total brain volumes, and was shown to associate with disease severity of Lewy Body dementia, independent of disease duration." (PMID 37178386, 2023). "We did show higher GDF15 to be associated with worse cognitive function and higher risk of dementia." (PMID 37178386, 2023). "In this two-sample MR study, we investigated the causal association between troponin T, troponin I, NT-proBNP, GDF15, and cognitive performance and dementia." (PMID 37178386, 2023). "In summary, our study did not provide evidence fully supporting a causal association between troponin T, troponin I, NT-proBNP, and GDF15 with cognitive performance and dementia." (PMID 37178386, 2023). "Several studies in humans have found an association between high circulating levels of GDF15 and the risk of dementia, cerebrovascular disease, cognitive impairment, and brain atrophy, which are clinical features of many neurodegenerative diseases." (PMID 36698863, 2022). "This was the first step of the present work, as previous studies have found an association between the circulating levels of GDF15 and the risk of dementia, cerebrovascular disease, cognitive impairment as well as brain atrophy, and AD." (PMID 36698863, 2022). "Some studies reported that higher levels of GDF-15 (plasma, serum, or cerebrospinal fluid) are associated with cognitive impairment and dementia, as well as with decreased gray matter volumes and white matter integrity." (PMID 33131010, 2021). "A MIC-1/GDF15 serum level exceeding 2764 pg/ml was associated with a 20% chance of decline from normal to MCI or dementia." (PMID 25867953, 2015).
dementia (continued). "However, a one SD increase in plasma GDF15 was associated with an 11% increase [HR: 1.11; 95% CI: 1.02–1.22] in dementia risk after adjusting for age and sex (p = 0.02)." (PMID 41274863, 2025). "Despite an overlap of only 12%–36% of variation between DNAm GDF15 and plasma GDF15 across the three cohorts, the two measures showed relatively similar associations with dementia risk and ADRD‐related brain atrophy; however, we found the former was a stronger predictor of cognitive decline." (PMID 41274863, 2025). "The current study provides evidence that epigenetic proxies of CRP and GDF15 exposure reflect the activation of immune/inflammation‐related pathways and are associated with longitudinal brain atrophy and cognitive decline as well as long‐term dementia risk." (PMID 41274863, 2025). "Despite these limitations, the current study demonstrates that epigenetic proxies of CRP and GDF15 exposure reflect the activation of immune/inflammation‐related pathways associated with accelerated brain atrophy, cognitive decline, and long‐term dementia risk." (PMID 41274863, 2025). "GDF-15 was reported to be associated with cognitive impairment and dementia in general populations." (PMID 38397960, 2024). "Therefore, in this study, we aimed to evaluate the association of troponin-T, troponin-I, NT-proBNP and GDF15 with cognitive performance and risk of dementia using Mendelian Randomization." (PMID 37178386, 2023). "Finally, we related DNAm/plasma CRP and GDF15 to dementia risk in two external cohorts." (PMID 41274863, 2025). "Among the most important mediators was GDF15, which is a stress-response protein that plays a multitude of roles in disease processes, but recently has been linked to the immunological response to infection as well as playing a potential role in cognition and dementia." (PMID 39080466, 2025). "Additionally, we compared the performance of the CRP and GDF15 DNAm scores to that of their plasma protein counterparts and determined whether the DNAm associations extended to near‐ and long‐term dementia risk in two independent cohort studies." (PMID 41274863, 2025). "Ultimately, whilst GDF15 upregulation in AD pathogenic models and ex vivo tissue is inconsistently demonstrated, it may have potential utility as a biomarker for AD and other dementias." (PMID 39737171, 2024). "For example, per standard deviation (SD) higher cardiac blood biomarker, the odds ratio for risk of dementia was 1.06 (95%CI 0.90; 1.21) for troponin T, 0.98 (95%CI 0.72; 1.23) for troponin I, 0.97 (95%CI 0.90; 1.06) for NT-proBNP and 1.07 (95%CI 0.93; 1.21) for GDF15." (PMID 37178386, 2023). "However, whether association between troponin-T, troponin-I, NT-proBNP and GDF15 and dementia is potentially causal remains unclear." (PMID 37178386, 2023). "Elevated GDF15 levels have been observed in patients with neurodegenerative and cerebrovascular diseases, including AD, PD, and dementia, where plasma concentrations of GDF15 correlate with disease progression and cognitive impairment [1005, 1265, 1275–1277]." (PMID 40407975, 2025). "The greatest risk was conferred by the highest quartiles of GDF15, TNFR1, MMP1, MMP7, and μPAR, with participants in Q4 for each biomarker having a HR ≥ 1.6 for incident dementia relative to those in Q1." (PMID 39695064, 2025). "In patients with Lewy body disease, the levels of GDF15 were positively correlated with age at onset of PD and dementia, Hoehn & Yahr stage, and t‐Tau and p‐Tau levels in cerebrospinal fluid, and negatively correlated with Mini‐Mental State Examination." (PMID 35068064, 2022). "Within Lewy body disorders, GDF15 levels correlated positively with age at onset of Parkinsonism and dementia, Hoehn & Yahr stage and cerebrospinal fluid t-Tau and p-Tau levels, and negatively with the Mini Mental State Examination." (PMID 26938614, 2016). "The association between GDF-15 (in tertiles) with CIND and dementia, expressed as odds ratios with 95% confidence intervals." (PMID 27537582, 2016).
dementia (continued). "In the overall Lewy body disorder cohort, GDF15 was positively correlated with age at onset of Parkinsonism, age at onset of dementia, H&Y stage, and with the neurodegenerative markers t-Tau and p-Tau." (PMID 26938614, 2016). "There were too few dementia patients in our sample to determine what the serum or CSF levels of MIC-1/GDF15 are once dementia develops." (PMID 25867953, 2015). "Elevated levels of GDF15 have been consistently observed in patients with neurodegenerative and cerebrovascular conditions such as Alzheimer's disease (AD), Parkinson's disease (PD), and various forms of dementia." (PMID 40295347, 2025). "Relative to plasma GDF15, DNAm GDF15 appeared to be more strongly associated with cognitive trajectories; however, this finding did not extend to brain volume trajectories or dementia risk." (PMID 41274863, 2025). "Emerging evidence has also connected GDF15 to cognition, dementia, and AD." (PMID 39080466, 2025). "Heterogeneity in the magnitude of the protein-dementia associations was observed among APOEε4 carriers for one NCR1 (one of the top four candidate proteins), GDF15, CHI3L1, and TFF3, each of which showed significant associations with VaD and comparatively weaker associations with AD dementia." (PMID 39482741, 2024). "Per SD higher GDF15, the odds ratio of dementia was 1.09 (95% CI 1.03; 1.15, p-value = 0.008)." (PMID 37178386, 2023). "Here, higher GDF15 was now associated with worse cognitive function (beta 0.12, SE = 0.05, p-value = 0.013), but not with higher risk of dementia (OR 0.79, 95% CI 0.51; 1.07, p-value = 0.107)." (PMID 37178386, 2023). "For dementia, NEFL, BCAN, GFAP, and GDF15 were the main proteins influencing disease risk." (PMID 38016990, 2023). "In addition, various blood markers of cardiac (dys)function such as troponin T and I, N-terminal pro B-type natriuretic peptide (NT-proBNP) and growth-differentiation factor 15 (GDF15) have been linked to worse cognitive function and subsequent dementia." (PMID 37178386, 2023). "We found similar results for the other cardiac blood biomarkers: per SD higher troponin I, NT-proBNP and GDF15, the odds ratio of dementia was 0.98 (95% CI 0.72; 1.23, p-value = 0.86), 0.97 (95% CI 0.90; 1.06, p-value = 0.46), and 1.07 (95% CI 0.93; 1.12, p-value = 0.32), respectively." (PMID 37178386, 2023). "Moreover, the direct correlation of CSF GDF15 with age at onset of Parkinsonism and dementia as well as the gender difference of the parameter suggests that GDF15 in CSF has some potential to detect prodromal phases of the disease." (PMID 26938614, 2016). "Moreover, GDF15 levels were positively and closely correlated with age at onset of Parkinsonism and dementia." (PMID 26938614, 2016). "Additionally, the GDF15 EpiScore association with incident dementia observed in Generation Scotland did not replicate in LBC1936." (PMID 39256775, 2024). "Elevated serum GDF15 is a feature of pregnancy and frequently observed in conditions like advanced cancers, chronic heart and renal failure, genetic mitochondrial diseases, obesity and type 2 diabetes, dementia and chronic inflammatory diseases, and is a reliable predictor of all-cause mortality." (PMID 39737171, 2024). "Addition of GDF15 and MMP1 modestly increased the C-statistic for dementia from 0.63 to 0.68." (PMID 39695064, 2025). "With respect to relative levels in plasma, GDF15 was increased in AD and dementia patients compared to individuals with no cognitive impairment." (PMID 39737171, 2024). "Prospective cohort studies have implied associations between blood levels of troponin T, troponin I, NT-proBNP, GDF15, dementia, and cognitive function, without providing evidence favoring possible causality." (PMID 37178386, 2023). "The association between GDF-15 (in tertiles) with CIND and dementia stratified by presence and absence of significant CeVD, expressed as odds ratios with 95% confidence intervals." (PMID 27537582, 2016).